AQP4 (aquaporin 4)
Diseases named in the same sentence as AQP4 in open-access papers (continued):
Sharing a sentence is not in itself a finding about the gene and the disease.
Hydrocephalus (continued). "Novel data confirm a dynamic response consisting of significantly decreased abundance of AQP4 in the periventricular region and cortex at two days and significantly increased periventricular abundance of AQP4 after two weeks of hydrocephalus." (PMID 21054845, 2010). "These authors also discussed the relative importance of astrocytic versus ependymal AQP4 in hydrocephalus." (PMID 20860832, 2010). "The AQP4 was first localized to the end feet of the astrocytes but later, the whole membrane of astrocytes became hypertrophic in severe cases of hydrocephalus." (PMID 20565964, 2010). "In summary, AQP4 abundance was found significantly decreased relative to control in both the periventricular region and in the cortex after two days of hydrocephalus and normalized after one week." (PMID 21054845, 2010). "After two weeks of hydrocephalus significantly increased periventricular AQP4 expression was observed." (PMID 21054845, 2010). "The functional significance of AQP4 during hydrocephalus has previously been investigated by using AQP4-null mice that show accelerated progression of ventriculomegaly relative to wild type controls." (PMID 21054845, 2010). "Immunoreactivity of AQP4 both in controls and hydrocephalic rats localised to the basolateral membrane of the ependymal cells lining the ventricular wall, thus confirming conserved polarisation of the AQP4 positive ependymal cells in hydrocephalus." (PMID 21054845, 2010). "There is a small but consistent rate of spontaneous hydrocephalus in AQP4-null mice that has been reported by several groups." (PMID 20860832, 2010). "In a hydrocephalus model in adult rats induced by L-α-lysophosphatidylcholine stearoyl (LPS), ventriculomegaly was correlated to increased AQP4 in astrocytes residing in periventricular areas such as in corpus callosum." (PMID 21054845, 2010). "Our observation of decreased abundance of AQP4 in the periventricular region after two days of hydrocephalus coincide with symptoms indicative of raised intracranial pressure (ICP) as judged by clinical symptoms." (PMID 21054845, 2010). "In hydrocephalus AQP4 has a protective effect by allowing resorption of transependymal CSF into brain capillaries." (PMID 20860832, 2010). "AQP4 levels are significantly altered in a time and region dependent manner in kaolin-induced hydrocephalus." (PMID 21054845, 2010). "AQP4 immunohistochemical analysis demonstrated the morphological expression pattern of AQP4 in hydrocephalus in astrocytes and ventricular ependyma." (PMID 21054845, 2010). "The authors concluded that the pattern of AQP4 expression was consistent with an adaptive response to the hydrocephalus." (PMID 20860832, 2010). "The present study shows regional- and time-dependent regulation of AQP4 expression in experimental hydrocephalus." (PMID 21054845, 2010). "The authors suggested that the increase in AQP4 reflected the development of a compensatory/alternative pathway for CSF resorption as is thought to occur in arrested hydrocephalus." (PMID 20860832, 2010). "In a model of obstructive hydrocephalus produced by injecting kaolin in the cisterna magna of mice, AQP4-null mice had accelerated ventricular enlargement progression compared with wild-type mice." (PMID 17347837, 2007). "AQP4 deficiency has been linked to accelerated hydrocephalus progression, while the absence of AQP1 appears protective against ventricular dilation." (PMID 40722587, 2025). "In experimental hydrocephalus models, such as kaolin injection into the cisterna magna, the upregulation of AQP4 has been observed in the hippocampus and cortex, indicating a possible compensatory mechanism aimed at enhancing CSF absorption and mitigating ventricular enlargement." (PMID 40722587, 2025). "It supported our research hypothesis that AQP4 took a role in the development of hydrocephalus after IVH." (PMID 37208490, 2024).
Hydrocephalus (continued). "We found that iron overload could affect the expression of AQP4 in the periventricular area, and the upregulated expression of AQP4 participated in the development of hydrocephalus after IVH." (PMID 37208490, 2024). "We speculated that the disparity in the role of AQP4 might originate from different mechanisms of hydrocephalus development." (PMID 37208490, 2024). "AQP4 is variable in the early stage but higher in the later stage, indicating that it compensates for reducing the production of CSF and the mechanism for the clearance of excess interstitial fluid in hydrocephalus." (PMID 39839745, 2024). "Significantly increased expression of AQP4 has been reported in several models, including the kaolin-induced hydrocephalus model in rats, Texas rats with congenital hydrocephalus, dogs with idiopathic obstructive hydrocephalus, and a rat model of inflammatory obstructive hydrocephalus." (PMID 39839745, 2024). "Osteopontin might be contributing to the rescue of aqueductal ependyma in AQP4−/− mice, preventing its occlusion and the development of obstructive hydrocephalus." (PMID 38956598, 2024). "Considering all rats received pentobarbital in our experiment, we speculated that the use of pentobarbital had a limited influence on the evaluation of the role of AQP4 in hydrocephalus." (PMID 37208490, 2024). "In addition, a higher level of AQP4 in ependymal cells was found in rats with hydrocephalus than in rats without hydrocephalus in the model of SAH, and the expression of AQP4 remarkably correlated with the severity of hydrocephalus." (PMID 37208490, 2024). "This increase in AQP4 expression was strongly correlated with the severity of hydrocephalus." (PMID 39839745, 2024). "In humans and experimental animal models of hydrocephalus, it has been proposed that these astrocytes can form a barrier that replaces the absent ependyma and contribute to alleviating edema in the white matter through AQP4 expression." (PMID 36982724, 2023). "Accordingly, silencing of AQP4 has been proven to aggravate hydrocephalus." (PMID 36982724, 2023). "Moreover, around 10% of AQP4 knockout animals develop hydrocephalus within 2–3 weeks after birth, which is about the same age others have noted a small but significant increase in brain water content in AQP4 null rodents." (PMID 37081555, 2023). "In the case of hyh mouse hydrocephalus, evidence indicates that the astrocyte reaction could have a protective effect, where AQP4 can play a relevant role in ependyma-denuded areas." (PMID 36982724, 2023). "In our study, the BM-MSC environment may explain the results of the stimulation of the astrocyte reaction, their AQP4 expression, and the presence of a neuroprotector effect in hydrocephalus development." (PMID 36982724, 2023). "Some models of hydrocephalus show increased AQP4 in the ependyma." (PMID 36293145, 2022). "Increased AQP4 expression found in human and rodent hydrocephalus may be a response to facilitate CSF clearance through the transependymal pathway." (PMID 36293145, 2022). "In addition, microvesicles from CSF in patients with obstructive hydrocephalus show increased AQP4 expression." (PMID 35346374, 2022). "The expression of AQP4 by the endfeet of astrocytes changes dynamically in hydrocephalus." (PMID 36226316, 2022). "Finally, we found that AQP4 is expressed in the microvesicle fraction (p < 0.01) of CSF from patients with obstructive hydrocephalus." (PMID 35346374, 2022). "AQP4 expression is increased in other types of hydrocephaly to drain extra CSF." (PMID 36204139, 2022). "Since glial activation is a characteristic phenomenon in hydrocephalus, where AQP4 is expressed in astrocytes, we propose that the presence of AQP4 in the CSF of pediatric hydrocephalic patients could derive from microvesicles released by astrocytes." (PMID 35346374, 2022). "However, in brain development, AQP4 is a marker of glial stem cells and plays a crucial role in the pathophysiology of pediatric hydrocephalus." (PMID 36142348, 2022).
Hydrocephalus (continued). "Contrary to other types of hydrocephalus, the expression of AQP4 shows a decrease in iNPH, which may allow treatment routes that affect AQP4 activation to have a more noticeable effect in iNPH than in other types of hydrocephalus." (PMID 36204139, 2022). "Brain aquaporin 1 (AQP1) and AQP4 are involved in cerebrospinal fluid (CSF) homeostasis and might participate in the origin of hydrocephalus." (PMID 34597351, 2021). "A very recent publication, that does not study AQP4, describes that young postnatal Vps35 conditional KO mice develop neonatal hydrocephalus, similar to that of Snx27−/− mice, with deficient ependymal cells differentiation and ciliogenesis." (PMID 34002021, 2021). "In addition, hydrocephalus has been reported in AQP4-IgG seropositive NMOSD patients as well as vasogenic edema that manifests as posterior reversible encephalopathy syndrome." (PMID 30691235, 2019). "While it is clear that AQP4 has a role in hydrocephalus, it remains unclear whether AQP4 has a protective or deleterious effect." (PMID 30691235, 2019). "Together, our results show that EPO-mediated upregulation of AQP4 significantly reduces dilation of the cerebral ventricles in obstructive hydrocephalus pups and may lead to potential therapeutic options for hydrocephalus." (PMID 29982881, 2018). "We therefore hypothesize that the severity and duration of hydrocephalus can be rescued by EPO-mediated upregulation of AQP4 by modifying CSF flow into the cerebral blood stream through AQP4 channels." (PMID 29982881, 2018). "Thus, AQP4 channels play a role in trans-parenchymal water clearance in obstructive hydrocephalus from the ventricle and extracellular space of the brain into the cerebral vasculature." (PMID 29982881, 2018). "Moreover, deletion of AQP4 potentiated the increases in intracranial pressure in a murine model of hydrocephalus consistent with the notion that AQP4 supports and facilitates intraparenchymal fluid flow." (PMID 30561329, 2018). "Based on the results of this study, a brain tissue-based determination of AQP4 at the mRNA and protein level might be rewarding to analyse the potential role of AQP4 in the compensation of extracellular fluid overload in dogs with communicating hydrocephalus." (PMID 27357498, 2016). "Therefore AQP4 and IL-6 in CSF can be indicators of ventriculomegaly, of cellular damage, and of improvement after the treatment of hydrocephalus." (PMID 27357498, 2016). "In addition, in a kaolin-induced hydrocephalus model, hydrocephalic Aqp4-null mice showed increased mortality rate, elevated intracranial pressures, and higher brain water content after kaolin induction compared to wild-type mice." (PMID 26526878, 2015). "Indeed, a subset of Aqp4-null mice developed obstructive hydrocephalus with elevated intracranial pressure." (PMID 26526878, 2015). "Aquaporin-4 expression is high in cerebrospinal fluid in hydrocephalus." (PMID 27379319, 2014). "An increase in CSF AQP4 in hydrocephalus is reported in a previous work and this may occur as a consequence of the loss of communication between ependyma and subsequent cell disruption; thus AQP4 would pass into the CSF." (PMID 27379319, 2014). "It is possible that AQP4 may freely leak from the parenchyma to the CSF during the early stages, when ependymal denudation is occurring and the hydrocephalus remains communicating." (PMID 23659378, 2013). "Many studies report that there is an up-regulation of AQP4 in animal hydrocephalus models which suggest that this up-regulation may be due to a compensatory effect of hydrocephalus." (PMID 23659378, 2013). "Therefore, all existing studies using animal models propose an adaptive and protective role of AQP4 to resolve hydrocephalic edema at the brain barriers in the pathophysiology of hydrocephalus." (PMID 23659378, 2013).
Hydrocephalus (continued). "AQP4 levels are significantly altered in kaolin-induced hydrocephalus, suggesting that AQP4 could play an important neurodefensive role in hydrocephalus and CSF disorders." (PMID 23659378, 2013). "It appears that aquaporin 4 may have a relevant role in hydrocephalus and be a useful therapeutic target [34, 54; reviewed by 40, 42, 56]." (PMID 22576081, 2012). "Also, in a kaolin injection model of obstructive hydrocephalus, AQP4 knock-out mice develop more marked hydrocephalus than wild-type mice, probably due to reduced water clearance through the ependymal and BBB." (PMID 21119878, 2010). "We hypothesize that pharmaceutical regulation of AQP4 may be used in the future to manage the clinical course and neurological outcome of hydrocephalus." (PMID 21054845, 2010). "Further studies therefore need to consider that pharmacological regulation of AQP4 may influence hydrocephalus in different ways." (PMID 21054845, 2010). "In order to test the hypothesis that AQP4 expression could be related to severity of hydrocephalus, we performed linear regression analysis of AQP4 expression relative to median of control group against lateral ventricular volume across all groups." (PMID 21054845, 2010). "The main role of AQP4 in hydrocephalus appears to be as a compensatory mechanism." (PMID 20860832, 2010). "The presented data suggest that AQP4 could play an important neurodefensive role, and may be a promising future pharmaceutical target in hydrocephalus and CSF disorders." (PMID 21054845, 2010). "However, the finding of AQP4 immunoreactivity in perivascular astrocytes in LPS-induced hydrocephalus support the data presented in this study showing time-dependent AQP4 changes following kaolin injection." (PMID 21054845, 2010). "We hypothesized that changes in AQP4 expression in specific brain regions correspond to the severity and duration of hydrocephalus." (PMID 21054845, 2010). "In this study we hypothesized that changes in AQP4 expression in specific brain regions correspond to the severity and duration of hydrocephalus." (PMID 21054845, 2010). "Hence our objective was to study the spatiotemporal changes in brain AQP4 expression during experimental hydrocephalus relative to healthy physiological conditions." (PMID 21054845, 2010). "Therefore, a structural deficit in the development of the ciliar ependyma, which would lead to a disturbance in the ciliary beat and thus to the rhythmic movement of the CSF in the AQP4−/− mice, would also be responsible for disorders such as the hydrocephalus reported in a number of these mice." (PMID 38956598, 2024). "While in the obstructive hydrocephalus model induced by kaolin injection, an elevated intraventricular hydrostatic pressure drove water movement from the ventricle into the parenchyma through AQP4 located on ependymal cells, presenting a compensatory effect for hydrocephalus." (PMID 37208490, 2024). "AQP4 may be a potential therapeutic target for hydrocephalus after IVH." (PMID 37208490, 2024). "Likewise, AQP4 global null mice have been reported to be vulnerable to induced hydrocephalus." (PMID 38077948, 2023). "Additionally, it was hypothesized that increased AQP4 expression might be a compensatory response to CSF absorption in static hydrocephalus." (PMID 36204139, 2022). "When this analysis was performed in aged animals, the increase in ventricular size was further enlarged in the wt and AQP1−/− animals but not in the AQP4−/− mice, indicating the participation of AQP4 upregulation in the hydrocephalus associated with hypoxia and aging." (PMID 35454119, 2022). "Moreover, AQP4-null animals develop more severe hydrocephalus than wildtype mice in a kaolin injection model of obstructive hydrocephalus; it is most likely due to decreased water clearance through the ependymal blood–brain barriers in AQP4-null mice." (PMID 35260880, 2022).
Hydrocephalus (continued). "Future studies that include the quantification of AQP4 in CSF could provide information about disease status, allowing for improved prognosis as well as the design of appropriate treatments for specific cases of hydrocephalus." (PMID 35346374, 2022). "Additionally, in hydrocephalus, AQP4 regulates CSF absorption." (PMID 36204139, 2022). "In addition, AQP4 is considered to have different roles for cytotoxic brain edema, vasogenic brain edema, and hydrocephalus, which may reflect to the different sites where water is accumulated in these conditions." (PMID 30691235, 2019). "AQP4-null mice exhibit an intact blood–brain barrier but a disorganized ependymal cell layer, even in animals without hydrocephalus, supporting a model in which loss of AQP4, whether genetic or antibody-mediated, induces defects in CSF homeostasis." (PMID 28184993, 2017). "Our findings also indicate that NMO is an “AQP4-opathy” with pathological targets beyond the astrocyte and provide insight into recent reports of edema and hydrocephalus in NMO patients that may suggest a unique model for CSF flow-dependent pathogenic events in this disease." (PMID 28184993, 2017). "Brain AQP4 up-regulation might be a compensatory response in dogs with hydrocephalus." (PMID 27357498, 2016). "Therefore, the increase of CSF AQP4 may be a consequence of ependymal disruption and the level of AQP4 in the CSF could be an indicator of the ependyma status and the stage of hydrocephalus." (PMID 27379319, 2014). "One can see that most of these studies, in hydrocephalus cases, used animal models (AQP4-knockout mice, H-Tx rats, and kaolin and L-α-lysophosphatidylcholine stearoyl-injection models of hydrocephalus), which indicate that there is an up-regulation of AQP4 expression at the BBB interface." (PMID 23659378, 2013). "Therefore, the increase of CSF AQP4 may be a consequence of the ependymal denudation and the level of AQP4 in the CSF could be an indicator of the ependyma status and the hydrocephalus stage." (PMID 23659378, 2013). "Although AQP modulating drugs are not currently available, studies are under way using high-throughput screening of chemical libraries to discover AQP4 modulators that could be used for treating several brain conditions including trauma, tumour, hydrocephalus and seizures." (PMID 21119879, 2010). "In recent times aquaporin 4, the most abundant aquaporin within the brain itself, which has also been shown to have a role in brain water physiology and relevance to brain oedema in trauma and tumours, has become an alternative focus of attention for hydrocephalus research." (PMID 20860832, 2010). "Additional, the cyclin-dependent kinase inhibitor olomoucine improved the redistribution of AQP4 from paravascular regions to the stromal space following GMH, effectively alleviating hydrocephalus induced in the GMH model." (PMID 39908266, 2025). "AQP4 and AQP1 are among the most extensively studied aquaporins, with AQP4 promoting CSF absorption during hydrocephalus events, and AQP1 serving as the basis for CSF secretion." (PMID 39908266, 2025). "The use of TGN-020 attenuated hydrocephalus development after IVH and inhibited the expression of AQP4 protein in the periventricular tissue between day 14 and day 28 without a significant effect on intraventricular iron deposition or ventricular wall damage." (PMID 37208490, 2024). "The present study focuses on the expression of AQP1 and AQP4 in the brain tissue and CSF of SHR and WKY rats to determine the time course of the development of spontaneous hydrocephalus and brain water balance along with chronic HT." (PMID 36293145, 2022). "This work analyzes the expression of the four most abundant aquaporins (AQPs) (AQP1, AQP4, AQP9, and AQP11) in the brains of mice and discuss their contribution to hydrocephalus." (PMID 35454119, 2022).